SOHLH1 (spermatogenesis and oogenesis specific basic helix-loop-helix 1)
Description:
Transcription regulator of both male and female germline differentiation. Suppresses genes involved in spermatogonial stem cells maintenance, and induces genes important for spermatogonial differentiation. Coordinates oocyte differentiation without affecting meiosis I (By similarity).
Synonyms: C9orf157; NOHLH; TEB2; bA100C15.3; bHLHe80; SPATA27; ODG5; SPGF32
Tractability: No criterion of Open Targets' tractability assessment is met for any kind of drug.
Gene: Protein-coding gene on chromosome 9 (135,693,407 to 135,704,498, reverse strand). Ensembl gene ENSG00000165643.
Subcellular location: Cytoplasm; Nucleus
Subcellular location (Human Protein Atlas): Nuclear speckles
Gene Ontology:
Molecular function: protein binding; DNA-binding transcription factor activity, RNA polymerase II-specific; protein heterodimerization activity; protein homodimerization activity; DNA-binding transcription factor activity; protein dimerization activity
Biological process: cell differentiation; oocyte differentiation; spermatogenesis; regulation of DNA-templated transcription; regulation of transcription by RNA polymerase II
Cellular component: chromatin; cytoplasm; nucleus
Genetic constraint (gnomAD): Loss-of-function variants: 22 observed, 32.03 expected, observed/expected ratio (o/e) 0.69, 90% interval 0.49 to 0.98. The synonymous counts are far from expectation, so gnomAD's model fits this gene poorly and the ratio says little. Missense variants: 496 observed, 419.92 expected, observed/expected ratio (o/e) 1.18, 90% interval 1.1 to 1.27. Synonymous variants: 248 observed, 192.32 expected, observed/expected ratio (o/e) 1.29, 90% interval 1.16 to 1.43.
Homologues: Orthologues: chimpanzee SOHLH1 (98% identical), macaque SOHLH1 (79% identical), dog SOHLH1 (47% identical), rat Sohlh1 (40% identical), mouse Sohlh1 (39% identical). Paralogues in human: SOHLH2 (13% identical).
Diseases named in the same sentence as SOHLH1 in open-access papers:
SOHLH1 is named in the same sentence as 15 diseases in open-access papers, as found by Europe PMC text mining. Sharing a sentence is not in itself a finding about the gene and the disease. The quoted sentences say what the papers report.
Infertility (6 papers, 2015 to 2025). "Conditional deficiency of either Sohlh1 or Lhx8 in the oocytes of primordial follicles causes massive primordial oocyte activation and postnatal oocyte depletion leading to infertility in mice." (PMID 37194006, 2023). "Loss of Sohlh1 or Sohlh2 causes infertility by disrupting spermatogonial differentiation into spermatocytes or ovarian follicle differentiation from primordial to growing follicles." (PMID 26375665, 2015). "Studies in mouse indicate that NOBOX, SOHLH1/SOHLH2 and LHX8 are co-expressed and cross-regulate each other, either directly or indirectly, thus controlling oocyte development during early follicular progression and therefore their mis-regulation leads to infertility." (PMID 39391877, 2024).
Azoospermia (5 papers, 2015 to 2025). Absence of any measurable level of sperm,whereby spermatozoa cannot be observed even after centrifugation of the semen pellet. "Other genes related to male infertility were identified to associate with azoospermia (e.g., SOHLH1, SYCP3, and TEX11)." (PMID 34442404, 2021). "Notably, multiple reports have indicated that certain mutations in the SOHLH1 gene are associated with non‐obstructive azoospermia (NOA)." (PMID 39950040, 2025). "Notably, these findings suggest a reevaluation of the impact of the c.346-1G>A mutation in the SOHLH1 gene on male infertility, as patients with this mutation exhibit diverse phenotypes that can manifest as azoospermia, normal sperm counts, or severe sperm malformations." (PMID 39950040, 2025). "Mutations in the SOHLH1 protein resulted in non-obstructive azoospermia." (PMID 36980830, 2023). "A splice-acceptor site mutation of the Sohlh1 gene also leads to nonobstructive azoospermia." (PMID 26375665, 2015). "At the genetic level, mutations in SOHLH1 gene have already been associated with non-obstructive azoospermia as well as genetic variants in SOHLH1 and SOHLH2 with non-obstructive azoospermia risk in Chinese men." (PMID 32164318, 2020).
male infertility (3 papers, 2021 to 2025). The inability of the male to effect fertilization of an ovum after a specified period of unprotected intercourse. "Intracytoplasmic sperm injection (ICSI) was successful in one case, highlighting the potential for genetic counseling and assisted reproductive technologies in managing male infertility attributed to SOHLH1 mutations." (PMID 39950040, 2025). "Studies in mouse models have demonstrated that knockout of SOHLH1 leads to abnormal differentiation of spermatogonia in male mice, resulting in male infertility." (PMID 39950040, 2025). "Therefore, in this study, we aimed to elucidate the genetic etiology of two cases of male infertility resulting from SOA and clarify the novel clinical phenotype associated with a heterozygous mutation at the c.346-1G>A site of the SOHLH1 gene." (PMID 39950040, 2025).
Hypergonadotropic hypogonadism (2 papers, 2022 to 2024). Reduced function of the gonads (testes in males or ovaries in females) associated with excess pituitary gonadotropin secretion and resulting in delayed sexual development and growth delay. "Moreover, exome sequencing analysis performed in two pairs of sisters with non-syndromic hypergonadotropic hypogonadism from two unrelated families revealed the presence of mutations in SOHLH1." (PMID 35972313, 2022).
premature ovarian failure (2 papers, 2015 to 2018). "Also factors such as Nobox and Sohlh1 are associated with human premature ovarian failure." (PMID 26076587, 2015).
asthenozoospermia (1 paper, 2025). "This study demonstrates that patients with severe oligozoospermia, asthenozoospermia, and teratozoospermia due to the SOHLH1 c.346-1G>A heterozygous mutation can be effectively treated with ICSI-assisted reproductive techniques, yielding a favorable prognosis." (PMID 39950040, 2025). "In this study, two patients with severe oligozoospermia, asthenozoospermia, and teratozoospermia were found to carry a heterozygous SOHLH1 mutation at the c.346-1G>A site." (PMID 39950040, 2025).
glioma (1 paper, 2025). A benign or malignant brain and spinal cord tumor that arises from glial cells (astrocytes, oligodendrocytes, ependymal cells). "Sohlh1 belongs to the superfamily of bhlh transcription factors and serves as a tumour suppressor in glioma." (PMID 40418209, 2025). "Taken together, our findings suggested that the Sohlh1/SFRP1/Wnt/β‐catenin signalling pathway represented one of the key molecular networks involved in the regulation of GSLC biology in glioma." (PMID 40418209, 2025). "The results showed that the expression of Sohlh1 was lower in glioma compared with the normal brain tissues, and the expression of Sohlh1 decreased with increasing tumour malignancy." (PMID 40418209, 2025). "Consistently, the overall survival of the glioma patients with high levels of Sohlh1 was higher than that with low expression of Sohlh1." (PMID 40418209, 2025). "Sohlh1 inhibited the proliferation, migration and invasion of glioma cells through upregulation of GSK‐3β expression." (PMID 40418209, 2025). "In GSLCs and glioma tissues, Sohlh1 expression was negatively correlated with the expression of GSLC markers, such as Nestin, CD133, CD44, SOX2 and OCT4, whereas Sohlh1 expression was positively correlated with the expression of GSLC differentiation markers, such as MAP2, GFAP and MBP." (PMID 40418209, 2025). "In addition, the analytic data from the CGGA database (in mRNASeq‐325) also showed that Sohlh1 expression in glioma tissues was negatively correlated with the expression of Nestin, a stemness marker." (PMID 40418209, 2025). "In this study, we found that Sohlh1 was highly reduced in GSLCs, compared to glioma cells." (PMID 40418209, 2025). "Our previous results have confirmed that Sohlh1 is a novel tumour suppressor in glioma." (PMID 40418209, 2025). "In addition, Sohlh1 was positively correlated with the expression of SFRP1, whereas negatively associated with the expression of Nestin in glioma tissues, suggesting a tumour suppressive role in the stemness of glioma." (PMID 40418209, 2025). "Clinically, we observed a significant inverse correlation between Sohlh1 and Nestin expression levels, and a positive correlation between Sohlh1 and SFRP1 expression in glioma tissues." (PMID 40418209, 2025). "We cultured glioma cells U87MG and U251 in vitro and constructed Sohlh1 overexpression and Sohlh1 knockdown stable cell lines by lentivirus transfection." (PMID 40418209, 2025). "Collectively, our findings suggest an important role of the Sohlh1/SFRP1/Wnt/β‐catenin pathway in regulating GSLC stemness and differentiation, suggesting potential therapeutic targets for glioma." (PMID 40418209, 2025).
ovarian failure (1 paper, 2015). "Previously, we discovered that global knockouts of germ cell-specific transcriptional co-regulators Sohlh1, Sohlh2, Lhx8, and Nobox, cause rapid oocyte loss and ovarian failure." (PMID 26076587, 2015).
spermatogenic failure (1 paper, 2025). A male infertility characterized by dirsuption of the process of sperm development from diploid cells into mature haploid spermatozoa. "In conclusion, this study identified the heterozygous mutation SOHLH1 c.346-1G>A in two patients with spermatogenic failure, associating it with reduced sperm count, impaired motility, and morphological abnormalities." (PMID 39950040, 2025).
triple-negative breast carcinoma (1 paper, 2022). An invasive breast carcinoma which is negative for expression of estrogen receptor (ER), progesterone receptor (PR), and human epidermal growth factor receptor 2 (HER2). "The two remaining M20 hub genes, SOHLH1, a transcription factor involved in spermatogenesis and folliculogenesis, and AFAP1-AS1, have also been demonstrated to promote triple-negative breast cancer cell proliferation and invasion." (PMID 35565356, 2022).
tumor (2 papers, 2023 to 2025). "Taken together, these results suggest that Sohlh1 markedly restrains the growth of intracranial tumours by controlling the stemness and differentiation of GSLCs in vivo." (PMID 40418209, 2025). "Bioluminescence imaging results showed that overexpression of Sohlh1 inhibited intracranial tumour growth and improved the survival of nude mice compared to the control group." (PMID 40418209, 2025). "Sohlh1 and Sohlh2 are both members of the bhlh family of transcription factors and are novel tumour suppressors." (PMID 40418209, 2025). "The AUC of anti‐FIRΔexon2 Abs + CEA (0.731) was higher than that of CEA (0.677) or anti‐SOHLH1 Abs + CEA (0.686) in patients with CRC when combined with clinically available tumor markers." (PMID 37964630, 2023). "Using Spearman's rank correlation analysis, we explored the existence of a correlation between anti‐FIRΔexon2, anti‐CFAP70, anti‐KARS, anti‐SNX15, or anti‐SOHLH1 Abs and clinically used tumor markers." (PMID 37964630, 2023). "We performed ROC analysis to evaluate the ability of candidate tumor markers—anti‐FIRΔexon2 and anti‐SOHLH1 Abs, to detect patients with CRC." (PMID 37964630, 2023). "Ectopic expression of Sohlh1 could restrain the growth of intracranial implanted tumours from GSLCs, whereas Sohlh1 induced the differentiation of GSLCs in vitro and in vivo." (PMID 40418209, 2025). "Next, we examined the effects of Sohlh1 on SFRP1 expression in GSLCs and GSLC‐derived tumour tissues." (PMID 40418209, 2025).
cancer (1 paper, 2023). A tumor composed of atypical neoplastic, often pleomorphic cells that invade other tissues.
SOHLH1 also shares sentences with these, for which no sentence is quoted: Obesity (1 paper); teratozoospermia (1); thymoma (1).